SLC11A1 (solute carrier family 11 member 1)
Diseases named in the same sentence as SLC11A1 in open-access papers (continued):
Sharing a sentence is not in itself a finding about the gene and the disease.
adenoma (1 paper, 2025). A neoplasm arising from the epithelium. "In the nomogram models for the “Adenomas and Adenocarcinomas” and “Cystic, Mucinous and Serous Neoplasms” subtypes, SLC11A1 exhibited the highest contribution." (PMID 41007849, 2025). "Specifically, GBP2 and P2RX7 were significantly downregulated in both the “Adenomas and Adenocarcinomas” subtype and the “Cystic, Mucinous and Serous Neoplasms” subtype (p < 0.001), while SLC11A1 and HCLS1 were significantly upregulated in these two subtypes (p < 0.01)." (PMID 41007849, 2025).
Alzheimer disease (1 paper, 2025). A progressive, neurodegenerative disease characterized by loss of function and death of nerve cells in several areas of the brain leading to loss of cognitive function such as memory and language. "Recent studies have found that SLC11A1 expression is significantly elevated in peripheral blood mononuclear cells of Alzheimer’s disease (AD) patients and is closely associated with antigen processing and presentation pathways." (PMID 41425581, 2025).
Aortic dissection (1 paper, 2023). Aortic dissection refers to a tear in the intimal layer of the aorta causing a separation between the intima and the medial layers of the aorta. "SLC11A1 and FGL2 are differently expressed in aortic dissection and may be involved in immune-inflammatory responses." (PMID 36755239, 2023).
breast carcinoma (1 paper, 2025). "We therefore developed a new macrophage-specific SPP1 TAM signature (PLAUR, SLC11A1, BRI3, FBP1, C15orf48) using publicly available scRNA-Seq data from lung, colorectal and breast cancers and validated the signature using multiple independently published scRNA-Seq datasets." (PMID 41415295, 2025).
diabetic neuropathy (1 paper, 2023). A chronic, pathological complication associated with diabetes mellitus, where nerve damages are incurred due to diabetic microvascular injury involving small blood vessels that supply these nerves, resulting in peripheral and/or autonomic nerve dysfunction. "For diabetic neuropathy, gene GFY (rs4802605), ADH4 (rs4148883), LRFN2 (rs61731010), PKHD1 (rs2499486), SLC11A1 (rs17235409), MATN4 (rs2072788), and PPARA (rs4253772) were associated or contributed to the biological relevance to the pathogenesis of the complication." (PMID 37033211, 2023).
Erythema (1 paper, 2025). Redness of the skin, caused by hyperemia of the capillaries in the lower layers of the skin. "Furthermore, interactions between ITPKC polymorphisms, including rs10420685, and other genes like solute carrier 11a1 (SLC11A1) have been found to influence the risk of KD and the erythema of the BCG injection site." (PMID 40114120, 2025).
gallstones (1 paper, 2024). Solid crystalline precipitates in the biliary tract, usually formed in the gallbladder, resulting in the condition of cholelithiasis. "We have developed a murine model of typhoidal chronic carriage by infecting NRAMP1+/+(SLC11A1) mice (129X1/SvJ) with gallstones that are induced by a 6–8-week lithogenic diet with Salmonella Typhimurium." (PMID 39619287, 2024).
hemochromatosis (1 paper, 2024). A disorder of iron metabolism characterized by a triad of HEMOSIDEROSIS; LIVER CIRRHOSIS; and DIABETES MELLITUS. "Seven GMs, including ABCC1, ADRB2, EDNRA, hemochromatosis (HFE), HLA, interleukin 8 (IL-8), TCF7L2, and SLC11A1, had two studies conducted." (PMID 40225935, 2024).
hepatocellular carcinoma (1 paper, 2022). A malignant tumor that arises from hepatocytes. "SLC11A1 was identified as a metabolism-related gene involved in predicting the prognosis of hepatocellular cancer." (PMID 36438826, 2022).
HIV-1 infection (1 paper, 2022). The type species of lentivirus and the etiologic agent of acquired immunodeficiency syndrome (AIDS). "Additional predictors of mortality in HIV-1 infection include genetic polymorphisms in iron regulatory genes, such as the SLC11A1 gene, encoding the natural-resistance-associated macrophage protein-1 (Nramp1), and the HP gene, encoding the free-hemoglobin scavenger haptoglobin." (PMID 35956266, 2022). "SLC11A1 gene mutations have been associated with increased susceptibility to infectious diseases, as well as diseases of chronic inflammation; however, the iron homeostasis contribution of Nramp1 and haptoglobin during HIV-1 infection remains an area of debate." (PMID 35956266, 2022).
Insulin resistance (1 paper, 2025). Increased resistance towards insulin, that is, diminished effectiveness of insulin in reducing blood glucose levels. "Additionally, in the PCOS group, increased expression of SERPINA1 and SLC11A1 was found to be associated with insulin resistance and inflammation, respectively." (PMID 40790236, 2025).
latent infection (1 paper, 2025). "miR-181a and miR-29b have been shown to target SLC11A1 and TIRAP, respectively, providing post-transcriptional regulation in latent infection states." (PMID 40565607, 2025).
leukemia (1 paper, 2013). A malignant (clonal) hematologic disorder, involving hematopoietic stem cells and characterized by the presence of primitive or atypical myeloid or lymphoid cells in the bone marrow and the blood. "Both EGR-1, found to associate at SLC11A1 locus 5' boundary (Section 5.2.2), and EGR-2 were involved in the induction of myelomonocytic differentiation of U937 and HL-60 leukemia cells as well as in MN activation." (PMID 24832660, 2013).
meningitis (1 paper, 2007). A disorder characterized by acute inflammation of the meninges of the brain and/or spinal cord. "While we did observe neurological deficits in a mouse line that normally resists lethal infection due to a wild type Slc11a1 allele (129S1/SvImJ), our current sample size does not permit detailed conclusions to be drawn regarding the impact of Slc11a1 status on meningitis development." (PMID 17597539, 2007).
metastatic melanoma (1 paper, 2025). A melanoma that has spread from its primary site to another anatomic site. "SLC11A1 was also associated with immune reduction in metastatic melanoma patients treated with targeted therapy." (PMID 41007849, 2025).
microcytic anemia (1 paper, 2013). Anemia in which the red blood cell volume is decreased. "In mammals, Nramp1 (Slc11A1) expression is restricted to macrophages, but a second Nramp protein, (Nramp2, Slc11A2, or DMT1), is localized in the plasma membrane of several tissues, and mutations have been linked to severe microcytic anemia and serum and hepatic overload." (PMID 24066281, 2013).
nonalcoholic fatty liver disease (1 paper, 2025). "Molecular docking coupled with molecular dynamics simulations was employed to evaluate the binding patterns and dynamic stability of Resmetirom—a drug approved for the treatment of nonalcoholic fatty liver disease in adults—with the protein structures of ERN1 and SLC11A1." (PMID 41378206, 2025).
osteomyelitis (1 paper, 2024). An acute or chronic inflammation of the bone and its structures due to infection with pyogenic bacteria. "The findings suggest potential linkages between SNPs in genes such as IL-1, IL-6, IFN-γ, TNF-α, VDR, tPA, CTSG, COX-2, MMP1, SLC11A1, Bax, NOS2, and NLRP3 with the development of osteomyelitis." (PMID 39301021, 2024). "Current research has amassed increasing evidence suggesting that SNPs in various genes, including IL-1, IL-6, IFN-γ, TNF-α, VDR, tPA, CTSG, COX-2, MMP1, SLC11A1, Bax, NOS2, and NLRP3, may contribute to the development of osteomyelitis." (PMID 39301021, 2024).
parasitic infections (1 paper, 2009). "SLC11A1 functions as a membrane transporter of divalent cations but its mechanism of mediating natural resistance to bacterial and parasitic infections remains unclear." (PMID 19768110, 2009).
pulmonary fibrosis (1 paper, 2022). Chronic progressive interstitial lung disorder characterized by the replacement of the lung tissue by connective tissue, leading to progressive dyspnea, respiratory failure, or right heart failure. "C1qa, Fcgr1, C1qb, C1qc, Ccr5, Slc11a1, Aif1, Emr1 and Cxcl10 were identified as the most closely connected module which were highlighted in yellow, including 9 nodes and 32 edges, and the genes in this region were upregulated in pulmonary fibrosis." (PMID 35078421, 2022).
respiratory infection (1 paper, 2017). "Since respiratory infection with Francisella alters the immune response compared to cutaneous infection, we sought to determine the role of Slc11a1 in intranasal Francisella infection." (PMID 28360906, 2017).
rheumatic diseases (1 paper, 2024). "The SLC11A1 gene, key in immune regulation and macrophage function, is linked to the susceptibility and severity of rheumatic diseases such as RA and SLE." (PMID 38675400, 2024).
vitamin A deficiency (1 paper, 2024). Deficiency of vitamin A due to malnutrition, malabsorption, or dietary lack. "Adoptive transfer of SLC11A1-proficient neutrophils, but not SLC11A1-deficient neutrophils, reduced systemic Salmonella burden in Slc11a1−/− mice or mice with vitamin A deficiency." (PMID 38374245, 2024).
infection (134 papers, 2006 to 2026). The state of being infected such as from the introduction of a foreign agent such as serum, vaccine, antigenic substance or organism. "Susceptibility to infection increased in Cebpe−/−Slc11a1+/+ mice compared with wild-type controls, in an Slc11a1-expression-dependent manner." (PMID 38374245, 2024). "The G169D Slc11a1 mutation causes deficiencies in macrophage activation and effector mechanisms (such as ROS and NO production), leading to intracellular pathogen infection susceptibility." (PMID 36792680, 2023). "We defined CC strains bearing Slc11a1 or Ncf2 mutations that unexpectedly survive acute STm infection." (PMID 35417454, 2022). "Intervals on Chr 1 contained Slc11a1 and Ncf2, known genes that have mutations linked to poor survival after STm infection." (PMID 35417454, 2022). "CC045 mice have mutations in both Slc11a1 and Ncf2, both typically leading to poor survival after STm infection." (PMID 35417454, 2022). "A point mutation in Slc11a1 (also known as Nramp1, or Ity) is associated with susceptibility to lethal systemic STm infection." (PMID 35417454, 2022). "CC045, the only strain to carry both Slc11a1 and Ncf2 mutations, is particularly unusual since 4 out of 6 mice of this strain survived STm infections." (PMID 35417454, 2022). "Polymorphisms in Ncf2 and Slc11a1, known to reduce survival in mice after STm infections, are located in the Chr 1 interval, and the Chr 7 association overlaps with a previously identified QTL peak called Ses2." (PMID 35417454, 2022). "Solute Carrier Family 11A Member 1 (SLC11A1), also known as natural resistance-associated macrophage protein 1(NRAMP1), has an immunoregulatory role in macrophage activation and the Th1/Th2 balance of the adaptive immune response to infection." (PMID 30953507, 2019). "SLC11A1 has been extensively associated with natural resistance to several infections in ruminants, including the Mycobacterium avium subsp." (PMID 29566643, 2018). "Further, it was observed that there was significant difference in allelic frequencies between cases and controls for SLC11A1 microsatellite (p=0.002) indicating an association between infection and SLC11A1 alleles." (PMID 28246455, 2017). "The expression of the solute carrier family 11 member 1 (SLC11A1) gene determines the susceptibility or resistance to in vitro infection with the H37Rvt strain of Mtb." (PMID 29085351, 2017). "In the mouse model, the Slc11a1/Nramp1 alleles influence theintrinsic ability of macrophages to resist infection by intracellular parasites." (PMID 26814595, 2016). "Our preliminary data highlight the potential significance of this gene in disease resistance in wild populations; further exploration of Slc11a1 will aid the understanding of susceptibility to infection in mammalian species of conservation significance." (PMID 25874773, 2015). "Most of our infection experiments used BALB/c mice that carry a dysfunctional Slc11a1 allele (see Introduction)." (PMID 23633950, 2013). "During infection, the SLC11A1 causes acidification of phagosomes which helps protect the host against infection." (PMID 23759115, 2013). "Susceptible strains (BALB/c and C57Bl/6) have mutant Slc11a1 gene, which allows rapid parasite replication in the liver during the first weeks of infection." (PMID 22912637, 2012). "Genotypic frequencies and associations of SNPs in IL10, IL10RA/B, TGFB1, and SLC11A1 with MAP-infection status." (PMID 20398313, 2010). "There is evidence that SLC11A1 gene is involved in modifying susceptibility to T1DM as shown by RNA silencing that inversely correlated with increased susceptibility to infection." (PMID 19768110, 2009). "Slc11a1 mutations found in inbred mice substantially affect the growth rates of microorganisms during experimental infections by Leishmania donovani, some Mycobacterium species (M. bovis, M. intracellulare, M. avium, and M. lepraemurium), and Salmonella enterica serotype Typhimurium." (PMID 36792680, 2023).
infection (continued). "Notably, this mouse genotype carries a mutation in Nramp1 (Slc11a1), a proton-coupled divalent cation transporter, which results in a permissive infection phenotype for S. Typhimurium." (PMID 35638781, 2022). "CC045 was also excluded, as it carries mutations in both Slc11a1 and Ncf2, yet survives infection." (PMID 35417454, 2022). "It has been found in the previous research that the Slc11a1 (solute carrier family 11 members 1, also known as natural resistance-associated macrophage protein [Nramp1]) gene, is involved in the susceptibility to pathogen infections in farm animals and has causal mutations." (PMID 36590113, 2022). "SLC11A1 encodes for iron channel, involved in cation metabolism and host resistance to infection." (PMID 31475010, 2019). "Mutation at Slc11a1 protein abrogrates its functions and macrophages carrying mutant Slc11a1 produce significant less amount of nitric oxide in response to intracellular infection." (PMID 29723216, 2018). "In macrophages, SLC11A1 regulates macrophage functions through inhibition of protein-tyrosine phosphatase activity, in turn modulating the signal pathways associated with NO production and the macrophage response to infection." (PMID 29723216, 2018). "Since SLC11A1+ B6 mice were resistant to intranasal LVS infection, we wanted to determine if Slc11a1 expression could compensate for the loss of TLR2." (PMID 28360906, 2017). "In inbred mouse strains, susceptibility to infection with several intracellular pathogens including Mycobacterium, Salmonella and Leishmania, is determined in part by the natural resistance-associated macrophage protein 1 (Nramp1) gene (Slc11a1)." (PMID 21731497, 2011). "Identification of the Slc11a1 gene aided our understanding of the susceptibility at early stages of infection in BALB/c mice, which reflects the strength of the innate immune response in controlling early parasite growth independently of acquired immune mechanisms." (PMID 21345200, 2011). "Indeed, polymorphisms in the Slc11A1 gene (encodes NRAMP-1) that compromise functionality are associated with increased susceptibility to infection by intracellular pathogens (e.g., M. tuberculosis and S. typhimurium), emphasizing the importance of this protein in the nutritional immune response." (PMID 26633519, 2015). "Indeed, mutations in Slc11a1 cause susceptibility to infection with Salmonella spp." (PMID 21345200, 2011). "Meanwhile, the expressions of Slc11a1, Havcr2, Ccl12, Sirt1, Ifng, Ccl3, and Trem2 were higher during the whole infection process." (PMID 40170749, 2025). "In mice, transcription factor HIF-1 regulates allelic variation in SLC11A1 expression by binding directly to the microsatellite during macrophage activation by infection or inflammation." (PMID 39775235, 2024). "The finding that SLC11A1 supports neutrophil-mediated host defences has important implications for immunity to infection." (PMID 38374245, 2024). "A functional NRAMP1 (Slc11A1) transporter has been described to be important for the control of infections with intracellular pathogens, including S.tm in mice." (PMID 34359992, 2021). "Some groups have shown that S. Typhimurium leads to inflammation in CBA mice (Slc11a1+/+), approximately 10 days after infection." (PMID 33735297, 2021). "The S. Typhimurium ΔgogAΔgtgAΔpipA mutant elicits severe inflammation in the cecum of Slc11a1 (previously Nramp1) +/+ mice compared to Slc11a1−/− mice at 4 days after infection." (PMID 33735297, 2021). "Searches for polymorphisms of the CARD15 (NOD2), SLC11a1 (NRAMP1), LRRK2, PTPN2/22 and VDR genes have been productive as they reveal susceptibilities for infection by mycobacteria due to impaired pathogen recognition or failure of phagosome maturation." (PMID 32033287, 2020). "The expression levels of SLC11A1 in both U937 and RAW264.7 cells were significantly increased after infection, and the induction of SLC11A1 in RAW264.7 seemed to be even stronger." (PMID 31069175, 2019).